CTLA4 (cytotoxic T-lymphocyte associated protein 4)
Diseases named in the same sentence as CTLA4 in open-access papers (continued):
Sharing a sentence is not in itself a finding about the gene and the disease.
tumor (continued). "In the lymph node, CTLA-4 outcompetes the stimulatory receptor CD28 for binding to T-cell ligands CD80 and CD86, which inhibit T-cell activity and thus promote tumor progression." (PMID 35664731, 2022). "CD8+ TEM tumour infiltration as a % of CD8+ cells was significantly higher in αPD1 monotherapy (** p < 0.01) and αPD1 + CTLA4 combination therapy (** p < 0.01) TRs compared to TNRs." (PMID 35267526, 2022). "Ipilimumab is a humanized anti-CTLA-4 antibody that blocks the interaction between CTLA-4 and its ligand and promotes T-cell activation to inhibit the tumor response." (PMID 36505771, 2022). "Among them, CTLA4, PD1, and PDL1 were all typical immune checkpoint molecules, closely related to tumor immune suppression." (PMID 39279987, 2022). "We observed significantly higher levels of exhaustion (ICOS, TIM3, CTLA4, PD1, LAG3, TIGIT) and activation (TNFSR9, CD69, CD25) markers for clonotypes restricted to the tumor." (PMID 36185254, 2022). "This study showed that there was high expression of immunosuppressive molecules such as PD-L1, CTLA4 and CD86 in the tumour tissue of PCNSL." (PMID 36061189, 2022). "We observed reduced expression of Ctla4 in carcinogen-induced mice administered the BRB-E diet compared to mice fed the control diet, suggesting a reduction in Treg activity in the tumor microenvironment of carcinogen-induced mice fed the BRB-E diet." (PMID 36016924, 2022). "The chronic inflammation induces immune exhaustion and dysfunction by firmly braking the immune activation signals via inducing expression of multiple IC molecules, including CTLA4, PD1, TIM3, LAG3, and TIGIT, in anti-tumor effector cells." (PMID 36211375, 2022). "We found that FoxP3 expression and ICs including PD-1, CTLA-4, TIM-3, and LAG-3 were significantly increased in tumor-infiltrating CD8+ T cells compared with NT and peripheral blood." (PMID 35804964, 2022). "We have previously demonstrated that for optimal tumor control, co-stimulatory antibodies such as OX40 antibody require different timing when compared to blocking antibodies such as anti-CTLA4 relative to the delivery of radiation therapy." (PMID 36056093, 2022). "Immune checkpoint (ICP) inhibitors, including PD-1, CTLA4, LAG3, and TIM-3, have potent tumor suppressor effects and can interfere with immune escape; these inhibitors are currently the first-line treatment options for multiple malignancies." (PMID 36203873, 2022). "Expressions of CD274, CTLA4, LAG3, PDCD1, PDCD1LG2, and SIGLEC15 were shown to be significantly different between normal and tumor samples in immune checkpoint analysis." (PMID 36588699, 2022). "The combination of radiotherapy and anti-CTLA-4 increases the diversity of TIL TCR repertoire, leading to increased tumour control in vivo; however, these tumours remain dominated by a small number of high-frequency T-cell clones." (PMID 36106115, 2022). "Compared with expanded T-cell clonotypes that were found in two or more tissues, expanded T-cell clones that were exclusively found in tumor demonstrated elevated expression of the proliferation marker MKI67 and the antigen-induced marker CTLA4." (PMID 36185254, 2022). "Immunophenoscore (IPS) further validated that the FAM72Alow tumor showed high immunogenicity and tended to respond to anti-PD1/PDL1/PDL2, anti-CTLA4 treatment, and combined immunotherapies." (PMID 36613817, 2022). "SIGLEC15, PDCD1LG2 (PD-L2), TIGIT, PDCD1 (PD-1), HAVCR2 (TIM3), CTLA4, LAG3, and CD274 (PD-L1) are transcripts related to immunological checkpoints that have a function in tumor immune evasion." (PMID 36042287, 2022). "Concerning immune therapies, the most pronounced clinical benefits have been observed with immune checkpoint blockers (anti-PD1/PDL1, anti-CTLA4 mAb), despite multiple cellular players comprising the TME and aiding in tumor progression and therapy resistance." (PMID 36077813, 2022).
tumor (continued). "The high-RS group showed a higher TIDE score, which indicated a higher potential for tumor immune evasion and a low probability to benefit from anti-PD1/CTLA4 treatment." (PMID 36467089, 2022). "Abundant studies have suggested that Foxp3 regulates the expression of several genes (CTLA-4, PD-1, LAG-3, TIM-3, TIGIT, TNFR2) involved in carcinogenesis to utilize its tumor suppressor function through knockout models." (PMID 36009853, 2022). "The expression levels of other hub genes CTLA4, CXCL10, CCL5, CCl4, ICAM1, CXCL9, CD27, GZMB, FCGR2A, SELL, IDO1 in SKCM were higher than those in non-tumor skin tissues (P < 0.05), and the results were statistically significant." (PMID 35710862, 2022). "CTLA4, HAVCR2, PVRL2, PDCD1, SIGLEC15, TIGIT, and VTCN1 expression levels were higher in tumor tissues, while CD244, LAG3, PDCD1LG2, and CD274 expression levels were found to be lower." (PMID 35923695, 2022). "When combining PI3K inhibitors with PD-1/CTLA-4 inhibitors, the MDSC level of tumor-bearing mice decreased significantly and was comparable to the control group." (PMID 35582531, 2022). "ELOVL1 was positively correlated with PD-1 (PDCD1), CTLA4, LAG3, endothelial growth factors (VEGFs), and so on, which are the common immune checkpoints in the HCC tumor-immune microenvironment (TIME)." (PMID 35912257, 2022). "In conjunction with targeting CTLA-4 and/or PD-1 and/or PD-L1, radiotherapy has been shown to induce CTL-mediated anti-tumor immunity in studies." (PMID 35337133, 2022). "Recent reports suggest that both CTLA-4 and PD-1 preferentially suppress CD28 signaling within the tumor, leading to reduced T cell activation, effector function, and metabolism." (PMID 35379805, 2022). "To examine the influence of immunotherapy on tumour growth and clonal dynamics, we compared WT mice treated with immunotherapy (anti-PD1 + anti-CTLA4) or control antibodies starting from day 10 when tumours were ~200 mm3." (PMID 36344500, 2022). "Since tumor cell–intrinsic PRC2 loss drives an immune-desert TME, we speculated that PRC2 loss might confer primary resistance to FDA-approved ICB immunotherapies, including anti–programmed cell death 1 (anti–PD-1) and anti–cytotoxic T lymphocyte–associated protein 4 (anti-CTLA4) antibodies." (PMID 35852856, 2022). "Immune checkpoints such as PD1, PD-L1, CTLA-4, and LAG3 are important in tumorigenesis, which can promote tumor immunosuppressive effects." (PMID 36160009, 2022). "The data revealed that the exhaustion status of CD8+ T cells was significantly improved in MPR tumor lesions, with reduced expression of exhausted markers, such as PDCD1, CTLA4, LAG3, and TIGIT." (PMID 35831283, 2022). "The anti-tumor efficacy was further significantly enhanced when combined with anti-PD1 and anti-CTLA-4 drugs." (PMID 36713375, 2022). "To obtain enough Treg cells, we analyzed splenic Treg cells and found that UDCA also reduced the population of splenic Treg cells and their TGF-β1, CTLA4, ICOS, and GITR levels in tumor-bearing mice." (PMID 35701426, 2022). "CTLA-4, LAG-3, Tim-3, and PD-1 receptors are transiently expressed following TCR activation and bind to ligands expressed at the surface of tumor cells and of some immune cells (DCs, monocytes, B lymphocytes)." (PMID 35454873, 2022). "Treatment with Pulsed XRT + anti-CTLA-4 led to significantly improved survival and resulted in a delayed tumor growth, where we observed enhanced antitumor efficacy at primary tumor sites beyond XRT + anti-CTLA-4 treatment group." (PMID 36275767, 2022). "CRC TI-Treg cells express immune checkpoint receptors including PD-1, CTLA-4, TIM-3, and the NTPDase CD39 that regulate their immunosuppressive phenotype and support tumor cells in escaping immune surveillance." (PMID 35874729, 2022). "The clinical success of CTLA-4 and PD-1/PD-L1 CPI has illuminated the utility of harnessing the immune system for generating anti-tumor responses." (PMID 35379805, 2022).
tumor (continued). "Given the therapeutic importance of the CTLA-4 pathway, efforts have been made to understand the mechanism of action of anti-CTLA-4 mAb such as ipilimumab and tremelimumab in anti-tumour responses." (PMID 36119113, 2022). "Herein, we aimed to detect the expression of CTLA-4, CD86, CD4, and CD8 in surgical specimens from RC patients after nCRT/nCT, and to classify CD4+ and CD8+ cells into stroma, tumor, and invasive categories according to their location." (PMID 36428666, 2022). "All together, these studies demonstrate that bispecific antibodies that target CHI3L1 and CTLA-4 have impressive antitumor effects while inducing CD8+ cytotoxic T cell differentiation and tumor cytotoxicity." (PMID 36618349, 2022). "It revealed that suppressing inflammasomes by knocking down Tmem176b in mice or utilizing TMEM176B inhibitors can improve the anti-tumor effect of CD8+ T and the efficacy of anti-CTLA-4 and anti-PD1 therapy." (PMID 35399535, 2022). "We show that 7HP349 in combination with anti–CTLA-4 and GVAX tumor vaccine results in synergistic, CD8+ T cell–dependent antitumor response in B16.BL6." (PMID 35552271, 2022). "Digital Spatial profiling protein expression analysis identified higher expression levels (p-value < 0.05 and FDR < 0.2) of two proteins (i.e., CTLA4 and OX40L) and lower expression of CD11c in tumor-adjacent stroma as compared to tumor epithelium." (PMID 36230846, 2022). "Anti-PD-1 mainly inhibits tumor proliferation by inducing tumor infiltration of CD8+ T cells, while anti-CTLA-4 plays an immunotherapy role by inducing CD8+ effector T cells and CD8+ T-cell proliferation." (PMID 36124030, 2022). "The outcome showed that the expression levels of CTLA-4 and PD-L1 were higher in Cluster 1 than Clusters 2 and 3, and the CTLA-4 expression was substantially greater in tumor tissues than in normal tissues." (PMID 35237659, 2022). "Immunotherapy has made revolutionized impacts on anti-tumor therapy, which performs its capacity by acting on specific molecular markers, including PD1, PD-L1, and CTLA-4." (PMID 35967384, 2022). "In addition, CTLA-4 tumour expression could also upregulate PD-L1." (PMID 35626149, 2022). "The discovery of the role of anti-CTLA-4 therapy on anti-tumor immunity ultimately led to the first and only FDA approval of anti-CTLA-4 immunotherapy to date, ipilimumab, in 2011." (PMID 35326731, 2022). "The combined inhibitors of IL-6 and CTLA-4, by contrast, improve the survival of LLC1 tumor-bearing mice." (PMID 36547898, 2022). "When cancer patients are treated with anti-CTLA-4 antibodies, CD8+ T cells are released from their anergy state and attack tumor cells, but at the same time, CD8+ T cells also attack normal cells that present cross-reactive antigens." (PMID 35159059, 2022). "In addition, decreased expression of PD-1 and CTLA-4 weakened the immune tolerance/anti-inflammatory function of the Treg population, whereas the number of central memory T cells with proinflammatory subsets increased, which contributes to tumor clearance and the inflammatory microenvironment." (PMID 36703957, 2022). "Eight days after tumor inoculation, mice were treated with the dual ICB therapy (anti-CTLA4 and anti-PD1 antibodies)." (PMID 35013216, 2022). "It was not clear how the expression and infiltration by TIM3+ LAG3+ CTLA4+ and PD1+ cells affect the tumor microenvironment in HGSC." (PMID 36359346, 2022). "Our results showed that the high-risk group with poor survival had a higher expression of T cell exhaustion markers, such as PDCD1/PD1, CTLA4, TIM3, LAG3, VSIR and TIGIT, which lead to tumor immune evasion." (PMID 36147509, 2022). "The expression of CD274, CTLA4, LAG3, PDCD1, PDCD1LG2 and SIGLEC15 was significantly different between adjacent normal tissues and tumor tissues." (PMID 36588699, 2022).
tumor (continued). "Combining entinostat with anti-PD-1 or anti-CTLA-4 significantly decreased the suppression by PMN-MDSCs, increased in activated granzyme-B producing CD8+ T cells, and improved the tumor-free survival in both breast cancer and pancreatic cancer." (PMID 35585567, 2022). "Significantly, the effect of anti-CTLA-4 depends on antibody-dependent cytotoxic activity (ADCC) to deplete CTLA-4-expressing Treg cells in the TME, and its deletion will abolish the anti-tumor effect of anti-CTLA-4." (PMID 36120342, 2022). "These humanized monoclonal antibodies target inhibitory receptors (e.g., CTLA-4, PD-1, LAG-3, TIM-3) and ligands (PD-L1) expressed on T lymphocytes, antigen-presenting cells, and tumor cells and elicit an anti-tumor response by stimulating the immune system." (PMID 35528727, 2022). "Immune checkpoint inhibitors (ICIs), such as anti-CTLA4, anti-PD1, and anti-PDL1, genetically engineered T-cell therapy like CAR T-cell therapy, have improved survival in tumor patients." (PMID 35651805, 2022). "Most of the existing and ongoing immunotherapies (e.g. anti‐CTLA4 and anti‐PD1) are directed towards MMR‐defective tumours." (PMID 35043584, 2022). "Tumor cells can evade T cell-mediated killing by upregulating the interaction of ligands (such as PD-L1) with the inhibitory receptor PD-1, CTLA-4, and LAG-3, which are expressed on tumor-infiltrating T-cells." (PMID 35281003, 2022). "Co-administration of VEE-TRP-2 particles with CTLA-4 mAbs and GITR mAbs resulted in tumor regression in 50% and 90% of mice, respectively." (PMID 36140364, 2022). "CD8+ T cells in the lung of 4TO7-Lin28B tumor-bearing host included a smaller CD44+CD62L− T cell population and expressed lower CTLA-4 and granzyme B." (PMID 35173168, 2022). "Blocking CTLA-4 in their murine lung tumour model increased CD8+T cell infiltration and reduced tumour growth." (PMID 35479076, 2022). "CTLA-4 is another immunoinhibitory receptor expressed on activated T cells, the complex CTLA-4-B7 acts as a checkpoint inhibitor for anti-tumor T cells." (PMID 35015785, 2022). "It has been proposed that CTLA-4 in TEV acts as a scavenger for the CD80/CD86 pro-apoptotic ligands, thereby protecting tumour cells." (PMID 36011012, 2022). "In recent years, immune checkpoint inhibitors, such as CTLA-4 and PD-1/PDL-1 inhibitors, have improved the treatment status of advanced tumours." (PMID 35510041, 2022). "Anti-CTLA-4 antibodies boost T cell activation and the following anti-tumor response by blocking the interaction of CTLA-4 and CD80/86 and inducing immune responses to weak tumor antigens." (PMID 35152908, 2022). "While CTLA-4 binds to CD28 ligands (CD80/CD86) to hinder T-cell priming, PD-1 attaches to its ligands (PD-L1/PD-L2) on tumor cells to induce T-cell death and inhibit the effector functions of cytotoxic T cells (Tc cells)." (PMID 36298592, 2022). "Intratumoral heat-iMVA alone in syngeneically transplanted PRC2-loss AT3 (sgEed) tumors only mildly retarded the tumor growth; however, i.t. heat-iMVA, when combined with anti–PD-1 and anti-CTLA4 ICB treatment, significantly reduced tumor growth." (PMID 35852856, 2022). "The anti-CTLA-4 antibody can be used for blocking the CTLA-4 and stimulating the activity of T cells toward the tumor." (PMID 35273607, 2022). "A convolutional neural network (U-Net) for the assessment of aberrant CTLA-4 antibody staining using two independent antibody clones (MSVA-152R and CAL49) was trained and validated on 4582 tumor samples in this study." (PMID 35091676, 2022). "It is with hope that an increased number of immune checkpoints (such as CTLA-4, PD-1, LAG-3, TIM-3, and TIGIT) be documented, although some tumor patients show immunotherapy tolerance." (PMID 35392063, 2022). "For this purpose, surface molecules expressed at much higher levels on Tregs than T cells are used as targets, such as CD25, CTLA-4, GITR, 4-1BB, OX-40, LAG3, TIGIT, CCR4, and CCR8; tumor burden control has also been observed." (PMID 36159809, 2022).
tumor (continued). "CTLA-4 depletion in mice enhances antitumoral activity of CD8 T-cells and suppression of Tregs within the tumour micro-environment." (PMID 35595321, 2022). "In a mouse colon-26 tumor model, inhibition of receptor tyrosine kinase KIT enhances the anti-tumor activity of immune checkpoint inhibitors (anti-CTLA-4 and anti-PD-1) by selectively reducing immunosuppressive M-MDSC clusters." (PMID 35740594, 2022). "Blockade of CTLA-4 and PD-1 leads to reversal of CD8+ T cell dysfunction and subsequently tumor rejection." (PMID 36465184, 2022). "We noted additional increases in tumor cell death with simultaneous treatment of FRG and anti-CTLA-4 antibodies together, at least additive in nature." (PMID 36618349, 2022). "Anti-CTLA-4 antibody also binds to CTLA-4 on regulatory T cells (one of the immune suppressive cells) and eliminates them by ADCC in tumor tissue." (PMID 35205802, 2022). "PDCD1, CD274, CTLA4, LAG3, TIGIT, and HAVCR2 are important immune checkpoints responsible for tumor immune escape." (PMID 35252356, 2022). "Like PD-L1, CTLA-4 and CD73, Fas/FasL is hijacked by cancer cells to suppress the immune response and induce tumour immune evasion." (PMID 36011012, 2022). "The anti-angiogenic effect of propranolol as a single agent treatment was also observed when used in combination with anti-CTLA4 in both the MCA205 and MC38 tumor model." (PMID 35017664, 2022). "By inducing CTLA-4 upregulation on immune T-cells, cancer cells use the CTLA-4 pathway to escape and promote tumor growth." (PMID 35158822, 2022). "In pre-clinical models, tumor control with antigens that were suboptimal at engaging T cells is improved on treatment with anti-PD1 and anti-CTLA4." (PMID 35937775, 2022). "Further, combined induction of ferroptosis and immune checkpoint inhibitors (ICIs) indicated synergistic anti-tumor activity, providing significant avenues for future research might and potentially driving immunotherapy of cancer to promising results, especially on PD-1 and CTLA-4 targets." (PMID 36335094, 2022). "P2RX1 expression was significantly positively correlated with PDCD1 (r = 0.507, p = 3.84e-66), CTLA4 (r = 0.455, p = 6.07e-52) and CD274 (r = 0.351, p = 3.26e-30) in BC after adjusted by tumor purity." (PMID 35585027, 2022). "For instance, humanized monoclonal antibodies that are specific for inhibitory receptors (such as CTLA-4, PD-1, LAG-3, and TIM-3) and ligands (PD-L1) expressed on T lymphocytes, antigen-presenting cells, and tumor cells." (PMID 36298592, 2022). "Immunotherapy elicits mainly cytotoxic activities in the TME, especially tumor-infiltrating cytotoxic T lymphocytes, and dysregulated immune checkpoints (e.g., PD1, PD-L1, CTLA4, TIM3) enable immune invasion of tumor cells." (PMID 36209117, 2022). "Even when patients were stratified in quartiles depending on SMG1 expression in tumor samples, those with lower tumor levels of SMG1 displayed a CD8 phenotype with more abundance of cells expressing exhaustion markers (LAG3, PD-1, CTLA-4, TIM3, TOX)." (PMID 36443756, 2022). "Preclinical data involving modified CpG ODNs in murine models have demonstrated that intratumoral injections result in tumor regression along with tumor-specific T cell responses and upregulation of immune checkpoint genes including PD-L1, OX40, and CTLA4." (PMID 36031601, 2022). "SIGLEC15, PDCD1LG2(PD-L2), TIGIT, PDCD1(PD-1), CD274(PD-L1), CTLA4, LAG3, and HAVCR2(TIM3) are transcripts related to immunological checkpoints that perform vital functions in tumor immune evasion." (PMID 36253777, 2022). "Inosine enhanced tumor growth and reduced IFN-γ expression by T cells in anti-CTLA4–treated mice; however, with exogenous CpG added as costimulation, inosine increased T cell expression of IFN-γ, and tumor growth was suppressed." (PMID 35166235, 2022).